TRPS1 (transcriptional repressor GATA binding 1)
Diseases named in the same sentence as TRPS1 in open-access papers (continued):
Sharing a sentence is not in itself a finding about the gene and the disease.
angiosarcoma (3 papers, 2024 to 2025). A malignant tumor arising from the endothelial cells of the blood vessels. "Our observations stand in contrast to these findings, as 34.3% of our angiosarcomas exhibited unequivocal TRPS1 labeling, while in nine cases (25.7%), TRPS1 expression was deemed uncertain." (PMID 38902365, 2025). "In contrast, TRPS1 expression was less common in angiosarcomas (15.0%; 3/20), Kaposi sarcomas (25.0%; 2/8), and neurofibromas (22.7%; 5/17)." (PMID 39051323, 2024). "The difference in intensity, proportion, and H-score for TRPS1 expression between AFXs/PDS and angiosarcomas was statistically significant (p < 0.001)." (PMID 39051323, 2024).
cholangiocarcinoma (3 papers, 2022 to 2024). A carcinoma that arises from the intrahepatic biliary tree (intrahepatic cholangiocarcinoma) or from the junction, or adjacent to the junction, of the right and left hepatic ducts (hilar cholangiocarcinoma). "According to the documented literature and our data, the positivity of MGP, GATA3, and TRPS1 is extremely rare in other tumor types, such as cholangiocarcinoma and colorectal, gastric, and thyroid carcinomas." (PMID 36284362, 2022). "The majority (90.9%) of metastatic carcinomas of the digestive system (from gastric and colorectal adenocarcinomas, adenocarcinoma of the appendix, SCC of the tongue, and cholangiocarcinomas) were TRPS1-negative." (PMID 39449380, 2024).
colorectal cancer (3 papers, 2010 to 2024). A primary or metastatic malignant neoplasm that affects the colon or rectum. "Among these, ZEB1, SPARC, CDH1 and EpCAM were the most significantly differentially expressed genes between TRPS1-WT and TRPS1-MT cells and had been previously associated with colorectal cancer metastasis." (PMID 39307879, 2024). "Collectively, these results demonstrate that the TRPS1 mutation significantly promotes colorectal cancer metastasis by activating ZEB1 expression, thereby enhancing epithelial to mesenchymal transition." (PMID 39307879, 2024). "Next, we performed immunohistochemical (IHC) staining on genome-sequenced primary human colorectal cancers tissues to evaluate the correlation between the expression of ZEB1, CDH1 and TRPS1 mutation." (PMID 39307879, 2024).
extramammary Paget disease (3 papers, 2024 to 2025). A malignant neoplasm in which there is infiltration of the skin by neoplastic large cells with abundant pale cytoplasm and large nuclei with prominent nucleoli (Paget cells). "In dermatopathology, TRPS1 is used as a marker of mammary and extramammary Paget’s disease and is also expressed by a variety of primary cutaneous tumors, mostly of adnexal origin." (PMID 39449380, 2024). "In dermatopathology, TRPS1 emerges as a valuable tool, particularly in distinguishing primary from secondary extramammary Paget disease, especially when arising in non-perianal cutaneous sites." (PMID 39051323, 2024).
lung adenocarcinoma (3 papers, 2022 to 2025). A carcinoma that arises from the lung and is characterized by the presence of malignant glandular epithelial cells. "In addition, Lung adenocarcinoma and ovarian serous carcinoma can also exhibit diffuse positive expression of TRPS1." (PMID 40822238, 2025).
malignant phyllodes tumor (3 papers, 2022 to 2025). A phyllodes tumor with sarcomatous stroma. "It is also worth considering that TRPS1 is a marker of cartilage and bone development, and therefore, its utility is compromised when the differential diagnosis is primary or metastatic sarcoma or malignant phyllodes tumor with osteochondroid differentiation." (PMID 40025593, 2025). "Therefore, TRPS1 may not be used as a diagnostic tool to differentiate between metaplastic carcinoma and malignant phyllodes tumor." (PMID 40025593, 2025). "In the context of breast sarcomas, TRPS1 expression has been identified in malignant phyllodes tumors but not in liposarcoma or AS." (PMID 38902365, 2025). "Concerning mammary sarcomas, they observed high TRPS1 expression in malignant phyllodes tumors, while no expression was detected in other breast mesenchymal tumors, including AS." (PMID 38902365, 2025).
ovarian carcinoma (3 papers, 2024 to 2025). A malignant neoplasm originating from the surface ovarian epithelium. "This review explores the expression of TRPS1 in various cancers beyond breast tissue, such as prostate, lung, and ovarian cancers, and discusses its role as a diagnostic tool." (PMID 39518009, 2024). "In ovarian cancer, TRPS1 expression is seen in up to 20.3% of all ovarian carcinomas." (PMID 39518009, 2024).
ovarian serous carcinoma (3 papers, 2022 to 2026). "While TRPS1 has been associated with high-grade serous ovarian carcinoma, its role in early ovarian development remains underexplored." (PMID 41481707, 2026). "Our results showed that only 2.4% of ovarian serous carcinomas had focal MGP expression, which is lower than the reported positivity of GATA3 (~6%,) and TRPS1 (14%,)." (PMID 36284362, 2022). "Previous studies have shown that TRPS1 exhibits limited expression in certain tumors, such as lung squamous cell carcinoma, ovarian serous carcinoma, ovarian non-serous carcinoma, and salivary duct carcinoma." (PMID 40822238, 2025).
pancreatic cancer (3 papers, 2013 to 2025). "The results of our current study clearly suggest that PDGF exhibits its effects on both cell proliferation and the EMT phenotype by inducing miR-221 expression, which results in down-regulation of p27Kip1 and TRPS1 in pancreatic cancer cells." (PMID 23967190, 2013). "The results demonstrate that PDGF exhibits its effects on both cell proliferation and the EMT phenotype by inducing miR-221 expression, which results in down-regulation of p27Kip1 and TRPS1 in pancreatic cancer cells." (PMID 23967190, 2013). "The low expression of miR-217 in pancreatic cancer patients was confirmed in two gene expression datasets (GSE41372 and GSE60980), and the prognostic value of two target genes (ANLN and TRPS1), was estimated on clinical data from the Tumor Cancer Genome Atlas (TCGA)." (PMID 33925948, 2021).
prostatic adenocarcinoma (3 papers, 2024 to 2025). "Notably, the study revealed a surprising finding: a significant percentage of lymphatic and distant metastases in prostate adenocarcinoma retained TRPS1 positivity." (PMID 38902365, 2025).
adenoid cystic carcinoma (2 papers, 2024 to 2025). A malignant tumor arising from the epithelial cells. "TRPS1 expression has also been observed in adenoid cystic carcinoma of the head and neck and upper respiratory tract, as well as in those of breast origin." (PMID 39518009, 2024). "Regarding malignant salivary carcinomas, TRPS1 expression has been reported in 10% of adenoid cystic carcinomas, basal cell adenocarcinomas, and intraductal carcinomas." (PMID 39518009, 2024).
basal cell carcinoma (2 papers, 2023 to 2025). A carcinoma involving the basal cells. "This article seeks to evaluate the IHC expression of TRPS1 in cutaneous neoplasms with follicular differentiation, such as trichoblastoma (TB), trichoepithelioma (TE), and basal cell carcinoma (BCC)." (PMID 37366800, 2023). "Cutaneous squamous and basal cell carcinomas had over 90% expression of TRPS1." (PMID 40025593, 2025). "We hypothesized that TB, TE, and BCC may represent a continuum of follicular differentiation and anticipated that trichoblastomas and trichoepitheliomas would exhibit a distinct staining pattern of TRPS1, which would differ from that of basal cell carcinomas." (PMID 37366800, 2023). "Differential staining of TRPS1 may be utilized as a marker of follicular morphogenesis, such as in trichoblastoma (TB), trichoepithelioma (TE), and basal cell carcinoma (BCC)—cutaneous neoplasms with follicular differentiation." (PMID 37366800, 2023). "TRPS1 IHC demonstrated positivity in the tumor nests in six of thirteen (46%) trichoblastomas, nine of fifteen (60%) trichoepitheliomas, and five of fifteen (33%) nodular basal cell carcinomas." (PMID 37366800, 2023).
chondrosarcoma (2 papers, 2025). A malignant cartilaginous matrix-producing mesenchymal neoplasm arising from the bone and soft tissue. "Furthermore, considerable TRPS1 labeling was noted in extramammary osteosarcoma and chondrosarcoma." (PMID 38902365, 2025).
Cognitive impairment (2 papers, 2015 to 2026). Abnormal cognition is characterized by deficits in thinking, reasoning, or remembering. "Three genes (TRPS1, RAD21, and EXT1) are considered responsible for the most common clinical features, which include facial dysmorphism, ectodermal and skeletal anomalies, osteochondromas, and cognitive impairment." (PMID 41683676, 2026).
coronary heart disease (2 papers, 2019 to 2025). "These SNPs are located in the TRSP1 and TRIB1 genes that encode the transcriptional repressor GATA binding 1 and tribbles pseudokinase 1 proteins, respectively, which are associated with the predisposition to coronary heart disease, and with plasma lipid profile levels in different populations." (PMID 40563858, 2025). "Previous genome-wide association studies (GWAS) have shown that the TRPS1 (transcriptional repressor GATA binding 1) and TRIB1 (tribbles pseudokinase 1) genes located on chromosome 8q23-24 are associated with the predisposition to coronary artery disease (CAD) and with plasma lipid profile levels." (PMID 40563858, 2025). "In recent years, data from genome-wide association studies (GWAS) have shown that the genes coding for transcriptional repressor GATA binding 1 (TRPS1) and tribbles pseudokinase 1 (TRIB1) play an important role in plasma lipid profiles and act as risk factors for coronary heart disease (CHD)." (PMID 40563858, 2025).
disc degeneration (2 papers, 2019 to 2020). "In a second phase, between day 7 and day 14, IVD cells combined with DWJM showed a down-regulation of SOX2 and SOX9 together with an up-regulation of TRPS1, a chondrogenic transcription factor previously identified by us as chondroprotective and associated with the lower grade of disc degeneration." (PMID 32292779, 2020). "TRPS1 expression levels significantly decreased with increasing grade of disc degeneration." (PMID 31569377, 2019).
gastric adenocarcinoma (2 papers, 2024 to 2025). "Remarkably, we found all three cases of gastric adenocarcinoma to be TRPS1-negative." (PMID 39449380, 2024).
gastric cancer (2 papers, 2024 to 2025). A primary or metastatic malignant neoplasm involving the stomach. "In gastric carcinoma, TRPS1 expression is similarly heterogeneous." (PMID 39518009, 2024). "While some studies have reported that TRPS1 expression is seen in up to 45% of cases of gastric carcinoma, others have found little to no expression in these tumor types." (PMID 39518009, 2024). "The immunoreactivity for TRPS1 was also higher in advanced gastric carcinoma (stage III or stage IV) and in those that featured lymph node metastases." (PMID 39518009, 2024).
Intellectual disability (2 papers, 2021 to 2025). "Patients with TRPS Type I generally do not have intellectual disability or significant short stature and are usually caused by nonsense mutations in the TRPS1 gene." (PMID 40756095, 2025). "Type II involves a contiguous gene syndrome with abnormalities in both the TRPS1 and EXT1 genes, resulting in intellectual disability and multiple osteochondromas." (PMID 40756095, 2025).
leiomyosarcoma (2 papers, 2024). An uncommon, aggressive malignant smooth muscle neoplasm, usually occurring in post-menopausal women. "However, the utility of TRPS1 in distinguishing AFXs from leiomyosarcomas or sarcomatoid SCCs seems to be limited, particularly with the latter group." (PMID 39051323, 2024). "TRPS1 expression was prevalent in dermatofibromas (24/24), leiomyomas (8/8), AFXs/pleomorphic dermal sarcoma (PDS) (20/21), dermatofibrosarcomas protuberans (14/22), and leiomyosarcomas (6/8)." (PMID 39051323, 2024). "In our study, we found that TRPS1 expression was frequently observed in tumors of uncertain differentiation (AFX and PDS), tumors of fibrohistiocytic origin (DF and DFSP), and tumors of smooth muscle origin (leiomyoma and leiomyosarcoma)." (PMID 39051323, 2024).
lymph node metastasis (2 papers, 2013 to 2014).
salivary duct carcinoma (2 papers, 2022 to 2025). An aggressive, high grade adenocarcinoma that arises from the salivary glands. "Further investigation of MGP expression in other tumor types is needed, especially those for which relatively high TRPS1 or GATA3 expression has been reported, such as salivary duct carcinomas and pancreatic adenocarcinoma." (PMID 36284362, 2022).
scoliosis (2 papers, 2009 to 2014). A congenital or acquired spinal deformity characterized by lateral curvature of the spine. "In addition, targeted disruption of the Trps1 gene in the mouse causes craniofacial abnormalities, kyphoscoliosis and reduced trabecular bone in heterozygous mice, and a lack of vibrissae, scoliosis and abnormalities in the thoracic spine and ribs in homozygous mice." (PMID 19772620, 2009).
serous carcinoma (2 papers, 2022 to 2025). "The first case was that of high-grade serous carcinoma of tubo-ovarian origin metastatic to the breast, that showed TRPS1 positivity." (PMID 40025593, 2025).
skin tumors (2 papers, 2024 to 2025). "Data from the literature have shown that both benign and malignant adnexal skin tumors express TRPS1 to various degrees." (PMID 39449380, 2024). "Moreover, as previous studies showed TRPS1 positivity in skin tumors, cartilage, and bone; therefore, its higher rate of positivity in metaplastic cancers may be due to squamous/mesenchymal differentiation rather than a marker of breast origin." (PMID 40025593, 2025).
small cell lung carcinoma (2 papers, 2018 to 2024). Small cell lung cancer (SCLC) is a highly aggressive malignant neoplasm, accounting for 10-15% of lung cancer cases, characterized byrapid growth, and early metastasis. "Of note, however, is the fact that, in contrast to the mammary metastases, the metastases of non-mammary origin expressed TRPS1 in a weaker and more focal pattern, with the exception of a case of small-cell lung carcinoma that presented diffuse and strong TRPS1 positivity." (PMID 39449380, 2024).
sweat gland tumors (2 papers, 2023 to 2025). "In this study, we analyzed TRPS1 expression in a spectrum of cutaneous sweat gland tumors." (PMID 36810569, 2023). "Similarly, mucinous and sweat gland tumors (both benign and malignant) had high TRPS1 expression." (PMID 40025593, 2025).
synovial sarcoma (2 papers, 2024 to 2025). "TRPS1 is physiologically also crucial for bone and cartilage tissue development, and recent findings have highlighted its expression in synovial sarcomas." (PMID 38902365, 2025). "The potential use of TRPS1 in synovial sarcoma diagnosis is still under investigation." (PMID 39518009, 2024).
adenovirus infection (1 paper, 2015). "Expression of E-cadherin was increased in HIBECs following Trps1 adenovirus infection and CP/reperfusion injury (CPRI), with vimentin expression levels reduced and CPRI-mediated epithelial-mesenchymal transition (EMT) inhibited." (PMID 25886207, 2015).
alopecia (1 paper, 2009). Hair loss usually from the scalp. "The targeted disruptions of the Hoxc4,Hoxc13 and Trps1 genes were reported to cause defects in the thoracic vertebrae, alopecia, and abnormalities in the vibrissae, skull and thoracic vertebrae, respectively." (PMID 19772620, 2009).
apocrine carcinomas (1 paper, 2024). "A larger number of apocrine carcinomas need therefore to be studied in order to definitively assess the usefulness of TRPS1 in the differential diagnosis between primary and metastatic adenocarcinomas of the skin." (PMID 39449380, 2024). "Of note, however, is the fact that one recently-published case of apocrine carcinoma carrying a RARA::NPEPPS fusion was found to be TRPS1-positive." (PMID 39449380, 2024). "However, normal apocrine sweat glands and apocrine carcinomas were reported to be TRPS1-negative, suggesting that TRPS1-positivity in a cutaneous adenocarcinoma could favor its metastatic, rather than primary, origin." (PMID 39449380, 2024).
atherosclerosis (1 paper, 2026). A disease characterized by the build-up of fatty material and calcium deposition in the arterial wall resulting in partial or complete occlusion of the arterial lumen. "This study evaluates the associations of TRPS1 and TRIB1 polymorphisms with subclinical atherosclerosis (SA) and plasma lipid levels in Mexican individuals." (PMID 41972583, 2026).
benign prostate hyperplasia (1 paper, 2004). "Finally, the expression levels of TRPS1, EIF3S3 and MYC were measured in freshly frozen clinical samples of benign prostate hyperplasia (BPH), as well as untreated and hormone-refractory prostate carcinoma." (PMID 14997205, 2004).
bipolar disorder (1 paper, 2025). A disorder of the brain that causes unusual shifts in mood, energy, activity levels and the ability to carry out day-to-day tasks. "Certain TFs such as ETS1, MAF, SMARCA2, TRPS1, and CREB3L1 appear to modulate TF-tagged genes in multiple traits, which could be key elements linking AD, bipolar disorder, and schizophrenia through shared regulatory pathways." (PMID 39905509, 2025).
chronic obstructive pulmonary disease (1 paper, 2020). A chronic and progressive lung disorder characterized by the loss of elasticity of the bronchial tree and the air sacs, destruction of the air sacs wall, thickening of the bronchial wall, and mucous accumulation in the bronchial tree. "Other identified genes previously reported in GWAS to be associated with CVD-related traits were ELL2 (GWAS of BP, insulin and glucose), TRPS1 (GWAS of BP), PID1 (GWAS of stroke, lung function and chronic obstructive pulmonary disease) and WIPF1 (GWAS of resting heart rate)." (PMID 31999706, 2020).
cleft palate (1 paper, 2019). Cleft palate is a fissure type embryopathy that affects the soft and hard palate to varying degrees. "Our study aimed to characterize the craniofacial phenotype to understand the role of Trps1 in craniofacial development and gain insight on the cleft palate pathogenesis in Trps1 deficiency." (PMID 31130868, 2019). "Hence, it is unlikely that failure of tongue descent is the main underlying cause of cleft palate in Trps1 deficiency." (PMID 31130868, 2019).